GTSCR1 (Gilles de la Tourette syndrome chromosome region, candidate 1)
Gene: Long non-coding RNA gene on chromosome 18 (70,630,507 to 70,670,885, reverse strand). Ensembl gene ENSG00000263417.
Subcellular location: Membrane
Diseases named in the same sentence as GTSCR1 in open-access papers:
GTSCR1 is named in the same sentence as 1 disease in open-access papers, as found by Europe PMC text mining. Sharing a sentence is not in itself a finding about the gene and the disease. The quoted sentences say what the papers report.
Tourette syndrome (1 paper, 2015). A neurologic disorder caused by defective metabolism of the neurotransmitters in the brain. "One example was GTSCR1 (Gilles de la Tourette syndrome chromosome region, candidate 1), encoding a 137 amino acid long protein with proteomics evidence." (PMID 26720152, 2015).